FBXO27 (F-box protein 27)
Description:
Substrate-recognition component of the SCF (SKP1-CUL1-F-box protein)-type E3 ubiquitin ligase complex. Able to recognize and bind denatured glycoproteins, which are modified with complex-type oligosaccharides.
Synonyms: FBG5; FBX27
Tractability: No criterion of Open Targets' tractability assessment is met for any kind of drug.
Gene: Protein-coding gene on chromosome 19 (38,990,714 to 39,033,773, reverse strand). Ensembl gene ENSG00000161243.
Subcellular location (Human Protein Atlas): Nucleoplasm
Pathways (Reactome):
Immune System: Antigen processing: Ubiquitination & Proteasome degradation
Metabolism of proteins: Neddylation
Gene Ontology:
Molecular function: protein binding; ubiquitin protein ligase activity
Biological process: ERAD pathway; glycoprotein catabolic process; SCF-dependent proteasomal ubiquitin-dependent protein catabolic process
Cellular component: SCF ubiquitin ligase complex; cytoplasm; cytosol
Genetic constraint (gnomAD): Loss-of-function variants: 29 observed, 25.26 expected, observed/expected ratio (o/e) 1.15, 90% interval 0.85 to 1.56. The synonymous counts are far from expectation, so gnomAD's model fits this gene poorly and the ratio says little. Missense variants: 388 observed, 341.63 expected, observed/expected ratio (o/e) 1.14, 90% interval 1.04 to 1.24. Synonymous variants: 175 observed, 137.43 expected, observed/expected ratio (o/e) 1.27, 90% interval 1.12 to 1.44.
Homologues: Orthologues: chimpanzee FBXO27 (100% identical), rat AABR07002848.1 (79% identical), mouse Fbxo27 (78% identical), rabbit FBXO27 (69% identical), dog FBXO27 (62% identical), guinea pig Fbxo27 (49% identical), tropical clawed frog fbxo27 (46% identical). Paralogues in human: FBXO17 (58% identical), FBXO2 (38% identical), FBXO6 (36% identical), FBXO44 (35% identical), NCCRP1 (28% identical).
Diseases named in the same sentence as FBXO27 in open-access papers:
FBXO27 is named in the same sentence as 3 diseases in open-access papers, as found by Europe PMC text mining. Sharing a sentence is not in itself a finding about the gene and the disease. The quoted sentences say what the papers report.
diabetic cardiomyopathy (1 paper, 2024). Diabetic cardiomyopathy is a disorder of the heart muscle in people with diabetes. "Additionally, CREG1 is an important cardioprotective factor, inhibiting FBXO27 expression to prevent LAMP2 protein degradation, promoting autophagy in cardiomyocytes, and alleviating diabetic cardiomyopathy." (PMID 39639394, 2024).
infection (1 paper, 2014). The state of being infected such as from the introduction of a foreign agent such as serum, vaccine, antigenic substance or organism. "Infection of shRNAs against eight F-box proteins (FBXL5, FBXW5, FBXO3, FBXO4, FBXO5, FBXO24, FBXO25 and FBXO27) upregulated Snail1 protein levels (at least by 2-fold) compared with parental cells or cells infected with a control shRNA." (PMID 24157836, 2014).
tumor (1 paper, 2020). "The potential tumor-suppressing role of CLCNKB, FBXO27, and FXYD6 in PTC requires further validation." (PMID 33553144, 2020).